MYCN (MYCN proto-oncogene, bHLH transcription factor)
Diseases named in the same sentence as MYCN in open-access papers (continued):
Sharing a sentence is not in itself a finding about the gene and the disease.
tumor (continued). "MYCN amplification is associated with poor prognosis in NB patients, and there is evidence to the effect that MYCN cooperates with ALK in a synergistic manner to promote tumor growth." (PMID 27049722, 2016). "This raises the possibility that any novel therapies that target the MYCN pathway and prove useful in one of these tumours could be of significant value in the others." (PMID 25749049, 2015). "Tumour metabolites have also been shown to correlate with tumour-specific genetic mutations, for example, IDH1 mutation in glioma, SDH and VHL mutations in paraganglioma and MYCN amplification in neuroblastoma." (PMID 26348444, 2015). "When DA tumours were compared with IR tumours at the p < 0.01 significance level, 1786/34339 (5%) of the probes on the array detected differential expression, including both probes for MYCN (ILMN_1653761: p = 0.0001, fold-change 2.10; ILMN_2219767: p = 0.0002, fold-change 3.34)." (PMID 25749049, 2015). "It therefore appears that similar but independent evolutionary solutions affecting two different pathways have been selected for at different stages of the development of contralateral tumours in the same patient, with MYCN disruption the earlier event on each side." (PMID 25749049, 2015). "While it is possible that MYCN overexpression alone may be sufficient for human tumor formation, we suggest that additional changes in gene expression, which likely characterize transgenic tumors and cell lines, are required for engraftment and tumor growth." (PMID 26222553, 2015). "Tumours with MYCN amplification, whether localised or metastatic, are all categorised as high risk tumours in both North American Children's Oncology Group (COG) and European (SIOPEN) neuroblastoma studies." (PMID 25889326, 2015). "Moreover, inactivation of cdk2 is synthetic lethal in MYCN-amplified tumor cells and cdk2 was also proposed as a potential target for NB therapy." (PMID 26029996, 2015). "Only one tumor had both MYCN amplification and ATM deletion." (PMID 26053094, 2015). "Amplification of the MYCN oncogene is perhaps the strongest indicator of an aggressive tumor." (PMID 25973900, 2015). "Notably, we observe that MYCN-targeting miRNAs are preferentially downregulated during MYCN-driven tumor development, suggesting that MYCN negatively regulates the miRNAs by which it is targeted, to safeguard its own expression." (PMID 25294817, 2015). "MYCN did, however, convey increased colony-forming potential in this system, raising the possibility that MYCN overexpression alone might permit SAPs to form a viable neoplasm, where pro-proliferative and survival factors outweigh factors promoting cell death." (PMID 26222553, 2015). "Although this dataset does not contain survival data, the correlations between SPR expression and three important clinical NB parameters are highly significant: age at diagnosis (P = 1.9 · 10−23, MYCN tumor amplification (P = 7.9 · 10−15, and INSS stage (various P values < 0.05)." (PMID 26093909, 2015). "In a larger study, in which genomic real-time PCR was used to measure MYCN copy number in a more heterogenous group of tumours from patients treated under various protocols (including immediate nephrectomy), we confirmed that MYCN gain is a common event, but found no particular subtype association." (PMID 25749049, 2015). "Patients with MYCN-amplified (MNA) tumours had significantly fewer affected body segments." (PMID 25267348, 2015). "In addition, the role of the MYCN gene in promoting tumor invasion, particularly in NB cells, is well known." (PMID 26439802, 2015). "We hypothesize that the patients with focal lesions with MYCNsc tumours might have had this MYCN expression profile." (PMID 25267348, 2015). "Additionally, MYCN oncogene expression was downregulated in vitro and tumor cell growth was markedly reduced in vivo." (PMID 25695609, 2015).
tumor (continued). "Our finding that integrin α4 expression in patient tumor samples was associated with poorer prognosis in MYCN-negative tumors (including lower grade tumors) provides an additional potential tool for the group of tumors with the most ambiguous prognosis." (PMID 25973900, 2015). "Furthermore, this work showed that treatment with missense oligonucleotides against MYCN mRNA blocks tumor growth in this model." (PMID 24759734, 2014). "A number of technical and interpretation guidelines have been published by the INRG Biology Group covering the following issues: Tumor sampling/storing/reporting of the MYCN gene copy status, including analysis of heterogeneous MYCN amplified tumors, and the evaluation and reporting of SCAs." (PMID 25161957, 2014). "Interestingly, TRPM7 mRNA expression was found in all tumor samples, and was significantly correlated with both MYCN amplification (p = 2.3 × 10−7) and mRNA expression (p = 3.5 × 10−3 in a 2logPearson test)." (PMID 25277194, 2014). "Finally, 22 patients treated for NB in our institution between 1999 and 2011, for whom aCGH have been performed on tumour, were identified with amplification only located at the MYCN locus and were considered as a control group (group 3, n = 22)." (PMID 25013904, 2014). "Thus, AHR in NB is likely to act as a tumor suppressor and promote tumor differentiation by downregulation of MYCN." (PMID 24586395, 2014). "Indeed, among the targets of MYCN-responsive miRNAs (mir-17/92 cluster, mir-9 and mir-421) there are tumor suppressors and genes involved in the metastatic process." (PMID 24806581, 2014). "Based on activation of the PI3K/mTOR pathway in a murine transgenic NB model expressing ALKF1174L and MYCN, we demonstrated that combining an ATP-competitive mTOR inhibitor with crizotinib induced tumor regression, although the molecular basis for this result was unclear at the time." (PMID 25228590, 2014). "Overexpression of the MYCN protein outside the embryonal context could induce a break in the immunological tolerance and expose tumor cells to the attack of the immune system." (PMID 26029658, 2014). "The stage of the tumor at diagnosis, the age of the patient and the presence or absence of MYCN amplification are the basic parameters used for risk stratification to determine the management and treatment of this disease." (PMID 23135478, 2013). "Since secondary numerical and segmental chromosomal alterations are common findings in NB, this may explain why in qPCR MYCN copy number was lower in tumor vs. blood given that the assay measures relative dosage of the genes." (PMID 24131700, 2013). "MYCN has the ability to activate genes that increase the malignancy of the tumor and at the same time has the ability to repress genes that can prevent tumor formation or at least that can keep the tumor restricted to a more benign form." (PMID 23482921, 2013). "Thus, higher frequency of MYCN gene aberrations in undifferentiated or less differentiated tumors indicates an important function of MYCN gene in tumor malignancy." (PMID 23320395, 2013). "MYCN was found to down-regulate CCL2 expression, thus providing a mechanistic insight into the different composition of tumor-infiltrating lymphocytes in MYCN amplified vs. MYCN non-amplified high risk tumors." (PMID 23805414, 2013). "Evaluation of MYCN status in NB tumor was performed by FISH, array-CGH and qPCR." (PMID 24131700, 2013). "Interestingly, molecular and cytogenetic evaluation revealed amplification of the MYCN gene with overexpression of MYCN mRNA, which was also found in the primary tumor." (PMID 23882450, 2013). "Tumor cells with more than 10 copies of MYCN were considered as amplified." (PMID 23445749, 2013). "The folate-nanoliposomes entrapped MYCN siRNA can be specifically distributed in tumor tissues." (PMID 23806172, 2013).
tumor (continued). "The same group has discovered that MYCN non-amplified high risk NB tumors produce the chemokine CCL2 which attracts invariant (i) NKT cells to the tumor site." (PMID 23805414, 2013). "Thus the establishment of MYCN transgenic zebrafish with the uniform phenotype of the tumor cells shows better resemblance of the feature of human AML." (PMID 23554972, 2013). "Furthermore, in NB cell lines and tumor samples, MYCN stimulates B cell-specific Moloney murine leukemia virus integration site (BMI1) expression." (PMID 23373009, 2013). "MYCN amplification is an established marker indicating aggressive tumor progression of NBL." (PMID 23320395, 2013). "When performing this analysis for all up regulated MYCN target genes listed in the MYCNot database, significant enrichment could be seen for all tumor subtypes and cell lines." (PMID 23308108, 2013). "One of the early attempts to target MYCN evolved from the finding that retinoids inhibited MYCN expression as part of the widespread transcriptional changes retinoids induced in NB cells which resulted in tumor cell growth arrest and differentiation." (PMID 23373009, 2013). "Together with clinical and pathological features (i.e., age at diagnosis, stage, tumor grade, histology and DNA ploidy) MYCN amplification (MNA) contributes to the identification of high-risk patients and represents one of the best independent markers of adverse outcome and very poor survival." (PMID 23152863, 2012). "This discrepancy could partly be explained by the difference in gene dosage, with a higher expression of MYCN driving a more rapid tumor growth." (PMID 23284678, 2012). "Furthermore, these compounds are likely to be effective in both MYCN amplified and non-MYCN amplified patients since polyamine deregulation has been observed in both tumor groups." (PMID 23181218, 2012). "Many of these loci are significantly underexpressed in tumours with MYCN amplification." (PMID 21970883, 2011). "MYCN-amplified tumor is highly aggressive with poor outcome." (PMID 21501490, 2011). "To derive MYCN amplification-specific signatures, we compared stage 4- and 4+ tumor, and detected 4602 probesets within 1501 genes that may undergo splicing disruption, and 2318 transcript clusters with expression changes during MYCN status change." (PMID 21501490, 2011). "High CHD5 staining values were found to be significantly associated with INSS stages 1, 2, 3 (MYCN non-amplified) and 4s NB (n = 63), age at diagnosis <12 m (n = 63) and favorable tumor histology (n = 63); P < 0.001 for all the tested variables." (PMID 20950435, 2010). "In contrast, tumours from children over 18 months of age are usually metastatic at diagnosis, often become refractory to treatment, and exhibit many recurrent chromosomal imbalances and/or amplification of the MYCN oncogene." (PMID 19924232, 2009). "Comparing two types of childhood neoplasms associated with the nervous system, it is interesting to note the role of chromosome 17, and its interrelations with MYCN amplifications." (PMID 19352461, 2009). "Interphase fluorescence in situ hybridisation results of disseminated tumour cells in the bone marrow can be given only if MYCN amplification is present due to the higher error-proneness if segmental/numeric aberrations are evaluated in mixtures of normal and tumour cells." (PMID 19401703, 2009). "Amongst MYCN nonamplified stage 4 tumours, 1p22 and 1p34-p31 LOH was observed in association with 11q and/or 14q loss." (PMID 19192278, 2009). "Heterogeneous MYCN amplification requires meticulous analysis of the tumour specimen." (PMID 19401703, 2009).
tumor (continued). "Moreover, miR-92 is the only miRNA from the miR-17-92 cluster with a significant differential expression between MYCN amplified and MYCN single copy tumor samples (Mann-Whitney, Benjamini-Hochberg multiple testing correction, P < 0.05)." (PMID 19531210, 2009). "In contrast, MYC transcription factors, including MYCN, also sensitize cells for apoptosis, a function that should inhibit tumor formation and that could also be involved in spontaneous tumor regression." (PMID 18851746, 2008). "Taking into account the well-known prognostic value of MYCN amplification, the only genetic marker retained in clinical protocols in Europe at present, pertinent genomic stratification is especially needed in MYCN non amplified low stage and infant tumours." (PMID 17579628, 2007). "Finally, tumours presenting MYCN amplification in addition to segmental chromosome alterations (type 3 tumours) show highly aggressive clinical behaviour and a poor outcome." (PMID 17579628, 2007). "The interpretation of previous results may be hampered by the heterogeneity of techniques and by the inclusion of MYCN amplified tumours." (PMID 17579628, 2007). "It is possible that RA catabolism is an early event in the emergence of resistance to retinoids, and may precede the selection of tumour cells with modifications, such as MYCN amplification, that lead to enhanced survival." (PMID 15714209, 2005). "However at passage 24 (resistant tumour), MYCN amplification was double that of the other passages studied." (PMID 15292932, 2004). "Chromosome 11q loss (with frequent parallel loss of chromosomes 3p, 4p and/or 14q) was found exclusively in tumours without MYCN amplification and was significantly associated with poor event-free survival." (PMID 11506492, 2001). "We conclude that chromosome 11q loss defines a biologically distinct group of tumours without MYCN amplification that appear to have potential for aggressive metastatic growth." (PMID 11506492, 2001). "Both tumours were metastatic and had amplification of MYCN and deletion at 1p36." (PMID 11506485, 2001). "MYCN oncogene content was assayed in 47/51 tumours and found to be amplified in 17 (37%)." (PMID 10993641, 2000). "However, LOH on 1p was found in only 1 of the 13 tumours with increased NM23H1 copy numbers, and MYCN amplification of four copies occurred in only one other such tumour." (PMID 8932344, 1996). "Moreover, the tumor cells from DFMO-treated mice showed a reduced expression of MYCN and LIN28B, further supporting the hypothesis that DFMO inhibits tumorigenesis by targeting these critical oncoproteins." (PMID 40004600, 2025). "In addition, MYCN amplification inhibits interferon activity and chemokine expression, and its overexpression enhances tumor cell resistance to immune-mediated cytotoxicity through a variety of mechanisms, including MHC-I downregulation and inhibition of NK cell activation." (PMID 40115016, 2025). "Furthermore, MYCN demonstrates genomic control that extends beyond simple amplification; various studies indicate that the MYCN gene induces transcriptional addiction in NB, highlighting the essential dependence of these tumor cells on MYCN for survival." (PMID 40429864, 2025). "The absence of any significant R2* response to cabozantinib in tumours arising in the Th-MYCN/ALKF1174L mice is likely a consequence of their having a relatively poorer haemodynamic vasculature compared to the Th-MYCN mice, which we previously revealed using susceptibility MRI." (PMID 40359728, 2025). "Furthermore, while glycolytic genes (HK2, GAPDH, ENO1) correlate with poor survival, the analysis cannot establish whether their upregulation drives tumour aggression or is a secondary effect of MYCN‐mediated metabolic reprogramming." (PMID 41420301, 2025).
tumor (continued). "Reactivation of RORα could significantly improves the anti-tumor activity of etoposide and serve as a therapeutic strategy for MYCN-amplified NBs by blocking the dysregulation of molecular clock and cell metabolism mediated by MYCN." (PMID 40166471, 2025). "Therefore, we repeated our analyses excluding all tumor samples with MYCN amplification." (PMID 41294259, 2025). "We hypothesize that the selected combination successfully eradicated the tumor in three mice, but it is likely that “dormant” cancer cells persisted in the remaining two mice due to ongoing MYCN expression, allowing these cells to evade the treatment and cause the observed relapses." (PMID 40708972, 2025). "In addition to the direct oncogenic functions of MYCN that arise via its regulation of gene expression, it also affects the tumor microenvironment via cytokine-mediated interactions between immune cells and tumor cells." (PMID 39802403, 2025). "Additionally, we identified substantial shifts in the glycosyltransferase gene activity in MYCN-amplified samples, revealing novel glycosylation patterns that may further support tumor immune escape." (PMID 39860532, 2025). "SMO mutations may sometimes prevent long-term therapeutic benefits from occurring; in other circumstances, mutations in downstream components of the SHH pathway (for instance, MYCN or GLI2 amplifications) or in other pathways might render tumor cells resistant to these medications." (PMID 38391759, 2024). "We found MYCN amplifications in 23 tumors (20%), rearrangements affecting the TERT locus in 19 tumors (17%) and ATRX mutations in 12 tumors (10%), comprising 7 focal deletions, 4 missense or nonsense mutations and one tumor affected by a structural rearrangement (NBL54)." (PMID 39635126, 2024). "Importantly, MRP1 has been shown to regulate tumor response to chemotherapy in MYCN amplified NBs, and several other ABC transporters like ABCC3 and ABCC4 that are transcriptionally regulated by MYCN were found to be associated with poor disease prognosis in NB." (PMID 38660306, 2024). "Using a published single-cell RNA-seq (scRNA-seq) dataset of tumor cells from high-risk lesions lacking MYCN amplification, we inferred cell cycle status based on expression of cell cycle-associated genes and then assessed expression of numerous neuronal markers." (PMID 38095019, 2023). "In addition to the six potential prognostic factors, tumour stage, histology, MYCN amplification, age at diagnosis, the 11q aberration, and DNA ploidy, tumours with any type of segmental chromosome alterations characterised patients with a high risk of relapse." (PMID 37240360, 2023). "In using the neuronal marker STMN1 as a tumor marker for NB, the possibility of different regulatory mechanisms of STMN1 expression and appropriate cut-off values between low-risk NB and high-risk NB with 1p36 LOH and MYCN amplification should also be considered for risk classification." (PMID 37760452, 2023). "Also, unlike clinical HR-NBs, the NXS2 model is derived from a hybrid cell line, does not have MYCN amplification or overexpression, and has a high tumor mutational burden." (PMID 37835389, 2023). "Indeed, MYCN upregulates HDAC2 to repress the tumor suppressor miR-183." (PMID 38069407, 2023).